INS (insulin)
Diseases named in the same sentence as INS in open-access papers (continued):
Sharing a sentence is not in itself a finding about the gene and the disease.
Insulin resistance (continued). "And high BCAA supplementation caused lower insulin sensitivity compared to the STC group, which implied that high BCAA supplementation would cause insulin resistance in mice." (PMID 39267003, 2024). "Both HOMA2 indices are related, and higher β-cell function defined using HOMA2-B most likely reflects higher insulin demand because of higher insulin resistance." (PMID 37831076, 2024). "In a recent small randomized clinical trial on cognitively intact insulin resistance older adults, intermittent fasting for over 8 weeks showed improved insulin-signaling biomarkers." (PMID 39518747, 2024). "It has various functions to counteract metabolic syndrome, including alleviating insulin resistance by promoting insulin-independent glucose uptake into cells and facilitating fat burning." (PMID 38822022, 2024). "IL-6 causes insulin resistance by impairing the phosphorylation of insulin receptors and receptor substrate-1, inducing the expression of SOCS-3, a potential inhibitor of insulin signaling." (PMID 39051061, 2024). "HGF is pivotal in compensatory mechanisms for insulin resistance, correlating with β-cell mass increases and improved insulin signaling." (PMID 39063072, 2024). "Simultaneously, the activation of the inflammatory response can interfere with insulin signal transduction, reducing insulin sensitivity and leading to insulin resistance and compensatory hyperinsulinemia." (PMID 39453929, 2024). "Premenopausal women with obesity and the G allele of the rs2282679 SNV demonstrated reduced 25-hydroxyvitamin D levels and higher insulin levels, as well as increased insulin resistance." (PMID 38570479, 2024). "Cardiac insulin resistance was assessed through a glucose clamp test and evaluation of myocardial glucose uptake after insulin infusion." (PMID 39125938, 2024). "T2DM is a consequence of insulin resistance – where cells stop responding appropriately to insulin – and defective insulin secretion by pancreatic β cells." (PMID 38932879, 2024). "Initially, MET was a pioneering insulin-sensitizing drug (ISD) utilized to explore the impact of insulin resistance on PCOS." (PMID 38397951, 2024). "They had moderate insulin secretory dysfunction and mild insulin resistance with mildly abnormal glucose homeostasis." (PMID 38805513, 2024). "In insulin resistance, the body compensates by producing more insulin, creating the state of hyperinsulinemia." (PMID 39767708, 2024). "The triglyceride glucose (TyG) index and triglyceride-to-high-density lipoprotein cholesterol (TG/HDL-C) ratio are recognized as simple non-insulin-based insulin resistance indices." (PMID 38678275, 2024). "This suggests that higher HbA1C levels are influenced by both insufficient insulin production and insulin resistance." (PMID 38200577, 2024). "Insulin resistance, i.e., impaired sensitivity towards insulin, diminishes insulin effectiveness, prompting elevated insulin levels." (PMID 38337673, 2024). "Previous studies has shown that AMPK activation can increase glucose uptake independently of insulin, improve insulin resistance in skeletal muscle, and lower plasma glucose and lipid levels." (PMID 39095777, 2024). "A study using genetically modified mice showed that transgenic overexpression of RBP4 caused insulin resistance, whereas genetic deletion of RBP4 enhanced insulin sensitivity." (PMID 38672227, 2024). "Breastfeeding duration was associated with lower insulin resistance (HOMA-IR) and lower insulin secretion (HOMA-B)." (PMID 38772880, 2024). "The improved glucose tolerance of Endo1-KO mice compared with WT mice after 10 weeks on HFD was accompanied by a decrease in fasting blood glucose and insulin levels, resulting in a lower insulin resistance index (HOMA-IR) in Endo1-KO mice." (PMID 38716728, 2024).
Insulin resistance (continued). "Since insulin plays a critical role in regulating blood glucose homeostasis, the development of insulin resistance is one of the main factors contributing to the onset of type II diabetes, a condition already correlated with stress." (PMID 38901134, 2024). "Metabolic parameters were measured, including fasting blood glucose, fasting insulin, homeostasis model assessment of insulin resistance (HOMA-IR), triglyceride and glucose (TyG) index, and lipid profiles." (PMID 39421535, 2024). "The study further underlined oxidative stress, induced by increased iron deposition in beta- and liver cells, as a possible mechanism leading to cell damage and liver-mediated insulin resistance, higher insulin secretion, and glucose dysregulation." (PMID 39685901, 2024). "In large population studies, insulin resistance is measured with simple formulas using fasting insulin and glucose values." (PMID 39768899, 2024). "Propofol is thought to induce insulin resistance, reduce insulin-stimulated glucose uptake in skeletal and cardiac muscle, and attenuate insulin-mediated suppression of hepatic glucose output in rats." (PMID 39712697, 2024). "A debate emerged as to the primary pathogenetic defect of T2D: was it insulin resistance or suppressed insulin release from the pancreatic β cell?" (PMID 38299589, 2024). "Insulin resistance (IR) refers to the decreased or impaired insulin sensitivity of target organs or tissues, resulting in a reduced efficiency of insulin-stimulated glucose utilization." (PMID 39247923, 2024). "Dapagliflozin is sodium-glucose co-transporter 2 inhibitor that has also shown effects in restoring insulin sensitivity and neuroprotection in obesity-induced insulin resistance." (PMID 39897964, 2024). "We found as little as 1 minute of SCD improves postprandial glucose and insulin after a mixed meal, with at least 3 minutes needed to improve insulin resistance." (PMID 38572086, 2024). "Oral carrageenan exposure induced insulin resistance in mice and carrageenan inhibited insulin-induced increases in phospho-(Ser473)-Akt and PI3K activity in vivo in mouse liver and in human HepG2 cells." (PMID 39593091, 2024). "The level of IGF-1 is regulated by many factors (insulin resistance, insulin levels, lipids, vitamin D3, hormones, metabolic syndrome, and inflammatory parameters)." (PMID 38540997, 2024). "Houstis and colleagues reported that the generation of ROS in cultured 3T3-L1 adipocytes preceded insulin resistance and ROS scavenging improved insulin sensitivity." (PMID 39288128, 2024). "These states, characterized by either insulin resistance or hyperinsulinemia, lead to adaptations in cardiac insulin signaling." (PMID 39026321, 2024). "The majority of patients had their insulin levels measured within one month prior to COS, and we believe that the pre-ovulation insulin level can serve as a reliable indicator of the patient’s insulin resistance status." (PMID 38807145, 2024). "Insulin resistance (IR) is a state characterized by decreased sensitivity and response of the body to insulin, manifested by a reduced rate of glucose uptake by the tissues and inhibition of hepatic glucose production, ultimately leading to hyperglycemia." (PMID 38702717, 2024). "The recent literature has emphasized that the quality of dietary fat plays a pivotal role in influencing insulin sensitivity and increased insulin resistance, whereas polyunsaturated fatty acids (PUFAs) have been associated with enhanced insulin sensitivity." (PMID 39057535, 2024). "These factors trigger cytokine signaling proteins that impede insulin signaling receptor activation in pancreatic cells, thereby promoting insulin resistance (IR)." (PMID 39267759, 2024). "Factors known to interfere with insulin signaling and trigger insulin resistance include hyperlipidemia, inflammation, and oxidative stress." (PMID 39049964, 2024).
Insulin resistance (continued). "Significant reductions in endotoxin and glycemic parameters like glucose, insulin, and homeostasis model assessment for insulin resistance (HOMA-IR) were observed." (PMID 39599742, 2024). "In patients with insulin resistance, the ovary retains its normal insulin sensitivity, contrary to other tissues." (PMID 39596891, 2024). "Systemic insulin resistance accelerates the progression of non-alcoholic fatty liver disease, worsening insulin action and creating a harmful cycle." (PMID 39408297, 2024). "The typical characteristics of T2D include impaired insulin secretion and insulin resistance Excessive glucocorticoid exposure fosters the onset of hepatic steatosis, insulin resistance, dyslipidemia, hyper-glycemia, and central adiposity." (PMID 39226159, 2024). "To assess if the 3xTg-AD mice exhibit signs of insulin resistance/insensitivity, we employed the insulin tolerance test (ITT)." (PMID 38565895, 2024). "Another notable source of reactive oxygen species (ROS) generation in β cells is the heightened demand for insulin, particularly evident in cases of insulin resistance." (PMID 38904034, 2024). "E3 ubiquitin ligases contribute to insulin resistance via two main mechanisms, including direct targeting of insulin signaling molecules and indirect regulation of insulin signaling by targeting pro-inflammatory mediators." (PMID 39188976, 2024). "For example, in Turkey, serum 25-hydroxyvitamin D was found to be negatively correlated with insulin and homeostasis model assessment of insulin resistance (HOMA-IR) in children 5–17 years of age." (PMID 38836246, 2024). "Overall, our findings support the notion that aged mice display impaired glucose metabolism characterized by both insulin resistance and impaired insulin secretion." (PMID 38794702, 2024). "Chronic inflammation causes insulin resistance by activating SOCS3 and JNK, suppressing insulin signaling." (PMID 38397916, 2024). "Specifically, the LGA-IDM group displayed markedly higher uIMT and ruWT values, which correlated with the elevated levels of insulin, C-peptide, and insulin resistance measured by HOMA-IR (p < 0.001 for insulin and HOMA-IR, p = 0.018 for C-peptide)." (PMID 39518658, 2024). "When the body develops insulin resistance and the pancreas is unable to generate enough insulin to maintain blood glucose levels within normal ranges, type 2 diabetes develops." (PMID 38645750, 2024). "The binding of SCFAs produced by them to their receptors can significantly reduce fasting blood glucose, fasting plasma insulin, and insulin resistance index levels." (PMID 39272484, 2024). "The pathological features of type 2 diabetes are impaired insulin secretion, insulin resistance, or both." (PMID 39206262, 2024). "Fat accumulation in the liver is associated with not only hepatic insulin resistance, but also with systemic insulin resistance through skeletal muscle insulin resistance." (PMID 39610482, 2024). "During pregnancy, the demand for glucose and fatty acids remains high to support fetal development, often resulting in decreased insulin sensitivity and the onset of insulin resistance." (PMID 39339244, 2024). "Insulin resistance is a pathological condition in which the ability of insulin to influence glucose uptake via insulin-dependent transportation is impaired, thus a higher-than-normal concentration is required to maintain a normal glucose level." (PMID 38952394, 2024). "The aim of this study was to examine the association of insulin resistance (evaluated by the short insulin tolerance test [SITT]) with parameters related to obesity and insulin resistance." (PMID 38905235, 2024). "The systemic insulin resistance is coupled with hyperinsulinemia, a combined result of excessive insulin secretion by the β cells and reduced insulin clearance by the liver." (PMID 39873003, 2024).
Insulin resistance (continued). "Soon after the increase of NEFA concentration in human plasma, insulin resistance began to develop, and insulin sensitivity was one of the important factors to calculate the fat distribution." (PMID 38599825, 2024). "Insulin resistance, often occurringin heart failure patients, impairs myocardial energetics and the anabolic effectsof insulin." (PMID 39618874, 2024). "Concerning the molecular mechanisms underpinning the link between vitamin D and insulin resistance, it has been demonstrated that vitamin D enhances insulin receptor expression in muscle, liver, and adipose tissue, thereby improving insulin sensitivity." (PMID 39201651, 2024). "In normal pregnancy, insulin resistance occurs to meet the nutritional needs of the placenta and foetus, which is usually compensated for by increased insulin secretion and an adaptive increase in pancreatic beta-cell mass." (PMID 38783609, 2024). "Understanding how insulin resistance is responsible for increased insulin secretion is difficult when blood glucose concentrations are normal." (PMID 39769002, 2024). "Plasma fructosamine x insulin concentrations, a measure of insulin resistance, were increased (P = 0.047) in mildly diabetic obese pigs (n = 10) by 57% (from 3153±646 to 4933±1002 A.U.)." (PMID 38498469, 2024). "Studies have supported that that overexpression of PTP1B negatively affects protein tyrosine kinases, and in consequence, induces leptin and insulin resistance because insulin is unable to bind with INSR and finally leads to T2DM." (PMID 39759127, 2024). "Beta-cell function and insulin resistance were assessed based on indices calculated from glucose and insulin values obtained during the OGTT." (PMID 38550917, 2024). "Insulin resistance (IR) is a defined as a state where the body cells become irresponsive to the physiological insulin levels secreted in the blood." (PMID 38590830, 2024). "TBS was also negatively correlated with glycated hemoglobin, fasting glucose levels, fasting insulin levels and homeostasis model scores for insulin resistance." (PMID 39124655, 2024). "In this study, we found that fasting serum insulin levels increased, and insulin resistance was observed in T2DM rats and mice, which are consistent with previous studies." (PMID 39338366, 2024). "In insulin resistance, pancreatic β-cells increase insulin secretion to maintain normal glucose tolerance; however, when β-cells are incapable of increasing insulin secretion, the plasma concentration of glucose increases." (PMID 38673770, 2024). "Reduced insulin sensitivity or increased insulin resistance (IR) is defined as a reduced biological response of the target tissue, such as adipose tissue, liver, or muscle, to a given concentration of insulin." (PMID 38907293, 2024). "Obesity resulting from a high-fat diet serves as the primary precursor initiating the pathways of lipotoxicity and glucotoxicity, both of which are mediated by insulin through insulin resistance (IR)." (PMID 38397999, 2024). "In patients with type 2 diabetes or insulin resistance, the ability of insulin to stimulate skeletal muscle glucose transport is altered due to an impaired GLUT4 translocation to the muscle cell surface." (PMID 39337980, 2024). "In T2D, peripheral tissue insulin resistance can lead to compensatory increased insulin demand, where pancreatic beta-cells increase insulin production to overcome resistance." (PMID 38811550, 2024). "The efficacy of GA is largely due to its ability to stimulate insulin secretion from β cells, reduce insulin resistance, and inhibit the intestinal absorption of glucose." (PMID 39840111, 2024). "Skeletal muscles are the primary sites for insulin-induced glucose and lipid metabolism, which are altered due to insulin resistance in obesity and T2DM pathology." (PMID 38541736, 2024). "In contrast, male Gpr183–/– mice that also showed significantly higher insulin levels after HFSD were able to compensate for insulin resistance." (PMID 39545055, 2024).
Insulin resistance (continued). "Type 2 DM is characterized by a reduction in insulin secretion by pancreatic β cells, and by insulin resistance in target tissues, including the liver, muscle, and adipose tissue, ultimately leading to hyperglycemia." (PMID 38399315, 2024). "Results showed that exposure of myotubes to palmitate led to insulin resistance, evidenced by decreased insulin-stimulated AKT phosphorylation and glucose uptake." (PMID 38611884, 2024). "During the compensation stage, the body compensates for insulin resistance by increasing insulin secretion to maintain euglycemia." (PMID 38674910, 2024). "Insulin resistance in the primary insulin target tissues is a recognized abnormality that occurs before T2DM develops." (PMID 39768947, 2024). "Insulin resistance (IR) is defined as a reduction in cellular sensitivity to insulin, which results in a decline in the effectiveness of insulin in facilitating glucose uptake and utilization." (PMID 39720248, 2024). "ROS activates a variety of cellular oxidative stress sensitive pathways, which lead to decreased insulin secretion or even insulin resistance." (PMID 39691690, 2024). "Among NDM, we separated IS-NDM from IR-NDM, using a cutoff M-value of 5.5 mg × g−1 × min−1 (high-insulin clamp conditions at baseline) for insulin resistance." (PMID 39626509, 2024). "Interfering with insulin signaling at the receptor level, at PI3K/AKT, and/or at the downstream effectors is suggested to be the underlying cause of hepatic insulin resistance." (PMID 38967989, 2024). "Streptococcus is positively correlated with insulin, connexin, and the steady-state model evaluation index of insulin resistance." (PMID 38495787, 2024). "The INS inhibits glucose production and stimulates glucagon production, and research shows that insulin resistance, and thus the need for insulin, increases significantly after the 20th week of pregnancy." (PMID 39292698, 2024). "Silibinin (20 weeks/day IP, daily for 4 weeks) was shown to reduce fasting glucose and insulin levels, reverse insulin resistance, improve liver steatosis by suppressing oxidative stress and NF‐KB activation." (PMID 38726421, 2024). "In insulin resistance, abnormal hepatic insulin action is thought to be the main driver of insulin resistance, requiring higher circulating insulin levels to adequately control blood glucose levels." (PMID 39179999, 2024). "Metabolic score for insulin resistance (METS-IR) is a surrogate index to estimate insulin sensitivity." (PMID 39110699, 2024). "This disruption affects the insulin signaling pathway, resulting in diminished insulin sensitivity and the onset of insulin resistance (IR)." (PMID 38469369, 2024). "In states of systemic insulin resistance, mTORC1/mTORC2 signaling in β-cells is essential for increasing β-cell mass and enhancing insulin secretion." (PMID 39200096, 2024). "Another interesting observation from their study was a strong association between blood magnesium levels and BMI-SDS in the insulin-sensitive obese group, emphasizing a potential link between magnesium status and insulin resistance." (PMID 39429362, 2024). "Overall pattern of the associations between ETDRS subfield-specific retinal band thicknesses and the insulin resistance-related HOMA2-IR were inverse compared with the insulin sensitivity marker eGDR." (PMID 38431705, 2024). "As a first-line treatment for insulin resistance, metformin can improve insulin sensitivity and control blood glucose levels, which can also reduce androgen levels and improve ovulation." (PMID 38549135, 2024). "Insulin resistance (IR) refers to the reduced sensitivity of insulin-dependent organs and tissues to endogenous and exogenous insulin." (PMID 39695656, 2024). "Insulin resistance, also known as impaired insulin sensitivity, is the result of a decreased reaction of insulin signaling to blood glucose levels." (PMID 38392069, 2024).